MOG (myelin oligodendrocyte glycoprotein)
Diseases named in the same sentence as MOG in open-access papers (continued):
Sharing a sentence is not in itself a finding about the gene and the disease.
encephalitis (continued). "The clinical course of two of these cases matched previous reports from the literature, suggesting that patients contract anti-NMDAR encephalitis followed by anti-MOG IDDs." (PMID 31866928, 2019). "In our cohort, MOG antibody-positive serum or CSF in 15 (16.9%) patients in anti-NMDAR encephalitis was higher than those in other reports." (PMID 31507515, 2019). "Group 2 included 11 patients whose anti-NMDAR encephalitis occurred with MRI abnormality and symptoms compatible with demyelination (two MOG antibody-positive cases)." (PMID 31507515, 2019). "A total of 15 cases (15/89, 16.9%) with anti-NMDAR encephalitis had co-positive MOG antibody (serum or cerebrospinal fluid or both)." (PMID 31507515, 2019). "In MOG-EM, cases of encephalitis and seizures were described whereas these symptoms are rare in NMOSD." (PMID 30405519, 2018). "Recently, multiple research groups have described isolated cortical and subcortical syndromes in MOG-IgG-seropositive patients, highlighting the importance of encephalitis in this context." (PMID 29670575, 2018). "In the first case, a bilateral cortical frontal steroid-responsive encephalitis with ADEM-like lesions and ON was associated with MOG antibodies and mild inflammatory changes with intact myelin sheaths." (PMID 30555462, 2018). "We here report an atypical case with serum and cerebrospinal fluid MOG-Abs and a clinical picture suggestive for acute encephalitis." (PMID 28982346, 2017). "Future studies are needed to confirm the presence of DWM in NCSE, its clinical relevance in different settings, and whether it is present in other forms of encephalitis, besides the anti-MOG form." (PMID 40648981, 2025). "The co-occurrence of anti-LGI1 encephalitis and MOG-IgG is a rare phenomenon." (PMID 40703404, 2025). "Currently, sporadic cases of MOG antibody-positive encephalitis with normal brain MRI and some cases of MOG antibody-positive myelitis accompanied by a negative spinal cord MRI have been documented, which do not conform to the latest criteria proposed by the International MOGAD Panel." (PMID 40078175, 2025). "Here, we report a case of anti-LGI1 encephalitis combined with positive MOG-IgG." (PMID 40703404, 2025). "While the pathogenesis of MOG antibodies in encephalitis with normal brain MRI remains unclear, we propose that this type may be regarded as a new spectrum associated with MOG antibodies." (PMID 40078175, 2025). "Additionally, a non-randomized controlled study of 17 patients with anti-NMDAR encephalitis and coexisting anti-MOG antibodies found a male-to-female ratio of 14:3." (PMID 41584103, 2025). "Patients hospitalized at Children’s Hospital of Chongqing Medical University from January 2016 to May 2024, who were positive for MOG antibodies and exhibited encephalitis symptoms with normal brain MRI findings, were retrospectively analyzed." (PMID 40078175, 2025). "The pathological mechanism of MOG antibodies positive encephalitis with normal brain MRI imaging is unknown." (PMID 40078175, 2025). "Therefore, we present a report on 17 patients from our single center who have been diagnosed with MOG antibodies positive encephalitis, despite exhibiting normal brain MRI findings." (PMID 40078175, 2025). "We report a case of anti-LGI1 antibody encephalitis combined with MOG-IgG." (PMID 40703404, 2025). "Notably, acute encephalitis mediated by anti‐myelin oligodendrocyte glycoprotein (MOG) antibodies is a common neurological demyelinating disease in clinical practice, with 21.3% of patients experiencing seizures." (PMID 41299860, 2025). "Furthermore, patients with MOG antibodies positive cortical encephalitis have shown mild inflammatory changes in the cortex and subcortex without distinct demyelination." (PMID 40078175, 2025). "The occurrence of anti-LGI1 encephalitis alongside MOG-IgG is a relatively rare phenomenon." (PMID 40703404, 2025).
encephalitis (continued). "Interestingly, in our study, three children with only clinical symptoms of anti-NMDAR encephalitis had positive MOG antibodies, and four children with only clinical symptoms of MOGAD had positive CSF anti-NMDAR antibodies." (PMID 38438553, 2024). "Thus, we believe that the pathological significance of anti-MOG antibodies in overlapping encephalitis is substantial." (PMID 38895128, 2024). "Their disease phenotype was a monophasic MOG-Ab positive encephalitis." (PMID 39243465, 2024). "Therefore, for the clinical consideration of MOGAD or anti-NMDAR encephalitis, simultaneous testing of MOG-IgG and anti-NMDAR-IgG is necessary." (PMID 38438553, 2024). "Although this patient is a classic case of MOG antibody encephalitis with brainstem lesions, the clinical manifestations of MOG antibody encephalitis are very heterogeneous, which needs to be observed and verified by a larger sample of cases and long-term follow-up." (PMID 39121314, 2024). "Therefore, when there are clinical symptoms similar to viral encephalitis, cortical lesions on cranial MRI, and poor therapeutic effect, MOG antibodies should be tested as soon as possible to make an early diagnosis and use immunotherapy promptly." (PMID 38438553, 2024). "One of these patients was also diagnosed with MOG encephalitis." (PMID 37077567, 2023). "Thus, we report a rare case of anti-MOG antibody encephalitis (unilateral cortical encephalitis with bilateral meningeal involvement) in an adult patient." (PMID 36831826, 2023). "However, these phenomena, which include some degree of tailing and multi-centralization, are related to the severe clinical phenotypes and serious complications of some MOG antibody-associated diseases and anti-NMDAR encephalitis in clinical practice." (PMID 37407586, 2023). "When anti-NMDAR encephalitis patients have CNS demyelinating manifestations or demyelinating changes such as multiple patchy or punctate foci of signal abnormalities on head MRI, the presence of MOG antibodies should be considered." (PMID 38249740, 2023). "This may be explained by the increased atypical cases confirmed by the cell-based assays adopted in this study and the increasing MOG antibody tests in children with unexplained encephalitis and white matter lesions." (PMID 37153594, 2023). "Therefore, the possibility of overlapping MOG antibodies should be considered in clinical practice among such anti-NMDAR encephalitis patients." (PMID 38249740, 2023). "Further studies should investigate and confirm the occurrence of anti-MOG encephalitis in adults, especially because treatment and prognosis of anti-MOG may differ from AIE." (PMID 37954587, 2023). "Regarding gender, the proportion of male patients is higher than that of females for most diseases, except for MOG antibody-associated diseases, anti-NMDAR encephalitis, unclassified immune diseases, neuromuscular diseases, and seizures (gastroenteritis/diarrhoea)." (PMID 37407586, 2023). "In this study, we found that the proportion of increased cerebrospinal fluid protein in the MOG-AD group was significantly higher than that in the anti-NMDAR encephalitis group (p < 0.05), suggesting that the inflammation was more pronounced in MOG-AD patients." (PMID 38249740, 2023). "SARS-CoV-2-associated pediatric movement disorders or cerebellar impairment occurred in a minority in the context of known entities such as Guillain-Barré syndrome, Sydenham’s chorea, thiamine deficiency, ADEM, or encephalitis with known antibodies (NMDAR, MOG)." (PMID 37515734, 2023). "Therefore, it is reasonable to believe that MOG antibodies act as the “responsible antibodies” of cortical encephalitis." (PMID 36688157, 2022). "Subsequent retrospective studies reported that MOG-IgG could be detected in 2.0% to 14.2% of patients with anti-NMDAR encephalitis, and NMDAR-IgG was detected in 2.9% to 11.9% patients with MOGAD." (PMID 36009058, 2022).
encephalitis (continued). "Taken together, these pieces of evidence, together with our results revealed the need for subsequent studies to determine whether anti-MOG antibodies are merely “concomitant antibodies” in cortical encephalitis." (PMID 36688157, 2022). "Clinically, MOG antibody disease that involves the optic nerve and spinal cord resembles NMOSD, with sight loss and paresis, and in case of brain involvement it has a presentation similar to ADEM, with encephalitis." (PMID 35454978, 2022). "Beyond treatment, another factor that may influence the prognosis of patients with anti-NMDAR encephalitis, including that concerning cognitive decline, is represented by the co-existence of anti-MOG (anti-myelin oligodendrocyte glycoprotein)." (PMID 34827386, 2021). "Compared to typical anti-NDMAR encephalitis, we found patients with positive MOG-Ab had milder conditions, such as lower incidence of movement disorder (p = 0.003), seizures (p = 0.047), and lower PICU admission rate (p = 0.027), as well as better response to first-line immunotherapy (p = 0.036)." (PMID 34268281, 2021). "For patients who suffer from anti-NMDAR encephalitis combining with anti-MOG CNS demyelination, second-line immunotherapy is recommended when first-line treatment such as steroids, intravenous immunoglobulin G (IVIG) and plasma exchange has been proven ineffective to prevent the relapse of disease." (PMID 33716942, 2021). "It suggested that aside from NMDAR-IgG, MOG-IgG might also play a role in the pathogenesis of encephalitis." (PMID 34691028, 2021). "A recent systematic review and meta-analysis including all literature published until 24 October 2020 found no reports on Covid-19-associated MOG positive encephalitis." (PMID 34706651, 2021). "In recent years, some atypical presentations in MOG-ab-associated encephalitis (MOG-E) have been increasingly reported but have not yet been described well." (PMID 34691028, 2021). "Although our study did not include cortical encephalitis caused by other pathogens, during the screening of the literature we found that MOG-Ab can coexist with other antibodies, especially anti-NMDAR-Ab." (PMID 35046784, 2021). "This suggests that MOG-EM should be differentiated from viral encephalitis." (PMID 34093424, 2021). "However, these consisted of individual cases or small sample reports, and no systematic review of large-scale samples has summarized, to date, the characteristic features of the coexistence of anti-NDMAR encephalitis and anti-MOG IDDs." (PMID 31866928, 2019). "The majority of MOG-IgG-seropositive cases have ON, encephalitis with brain demyelinating lesions, and/or myelitis; thus, we propose the new term MOG-IgG-associated ON, encephalitis, and myelitis (MONEM) to encompass this group of patients with CNS demyelinating syndromes associated with MOG-IgG." (PMID 29670575, 2018). "We present a rare case of a child with fever of unknown origin, diagnosed with MOG-IgG-associated encephalitis, bronchopneumonia, and MOG-IgG seropositivity despite negative infection screening." (PMID 42255904, 2026). "Interestingly, visual hallucinations have previously been described in two MOG-IgG positive cases of older females, one with a rapid encephalitis like progression, and another one with acute onset of headache and fever, diagnosed with unilateral cerebral cortical encephalitis." (PMID 40757033, 2025). "However, MOG antibody-positive encephalitis is highly steroid-responsive in most cases." (PMID 38292807, 2024). "Given the well-documented increased in BBB permeability often observed in inflammatory autoimmune CNS diseases, such as myelin oligodendrocyte glycoprotein antibody–associated disease and anti-NMDAR encephalitis, we hypothesize that efgartigimod exerts its effects through dual mechanisms." (PMID 39421741, 2024).
encephalitis (continued). "The criteria requires evidence of a monophasic or relapsing acute ON, myelitis, and/or encephalitis along with radiological or electrophysiological findings consistent with CNS demyelination accompanied by MRI, fundoscopic, CSF, histopathologic, or clinical findings that are consistent with MOG-AD." (PMID 38975430, 2024). "The anti-NMDAR encephalitis patients had longer hospital and higher incidence of clinical manifestations including psycho-behavioral abnormalities, involuntary movements, speech disorder, and sleep disorder than the MOG-AD patients and autoimmune GFAP-A patients." (PMID 37153594, 2023). "However, MOG positivity with isolated encephalitis has been infrequently reported." (PMID 36447808, 2022). "Similarly, also MOG IgG were most often detected concurrently with NMDAR-encephalitis." (PMID 36384491, 2022). "Therefore, testing of MOG-ab is necessary in pediatric encephalitis." (PMID 34691028, 2021). "Cerebral cortical encephalitis (CCE) is a rare clinical phenotype of myelin oligodendrocyte glycoprotein (MOG) antibody-associated disease (MOGAD), which usually begins with seizures, headaches, and fever, and may be misdiagnosed as viral encephalitis in the early stages." (PMID 35046784, 2021). "Additionally, since this study was originally designed for the study of patients with possible ADSs, patients with encephalitis-like presentations, also described in association with anti-MOG antibodies, would not have been included in our cohort." (PMID 31545352, 2020). "Therefore, patients with anti-NMDAR encephalitis should also be tested for MOG-Ab." (PMID 31440204, 2019). "However, anti-MOG IDDS could also occur first, followed by anti-NMDAR encephalitis, and a certain type of pathogenic antibody may be critical in the course of disease." (PMID 31866928, 2019). "Regardless of whether a patient first presents with clinical symptoms of anti-NMDAR encephalitis or anti-MOG IDDs, if a patient develops new impairments during the course of immunity-regulating therapies, the potential co-occurrence of these two types of diseases must be considered." (PMID 31866928, 2019). "As such, anti-NMDAR encephalitis and anti-MOG IDDs could occur simultaneously or successively." (PMID 31866928, 2019). "In addition, anti-NMDAR encephalitis and anti-MOG inflammatory demyelinating diseases may occur either simultaneously or in succession." (PMID 31866928, 2019). "Previous case reports have shown that its efficacy in adult anti-NMDAR encephalitis, and in three patients with MOG and anti-NMDAR IgG double-positive encephalitis." (PMID 40145095, 2025). "Clinicians should consider testing for MOG and AQP4 antibodies when atypical features are present in anti-NMDAR encephalitis patients." (PMID 40611612, 2025). "CSF meningitis and encephalitis panels, oligoclonal bands, aquaporin-4 antibodies (neuromyelitis optica or NMO-IgG), myelin oligodendrocyte glycoprotein (MOG) antibodies, and angiotensin-converting enzyme levels were all negative." (PMID 40557027, 2025). "In recent years, simultaneous or sequential occurrence of MOG antibody disease and anti-NMDAR encephalitis in the same patient has been reported with increasing frequency." (PMID 38664672, 2024). "We identified a case of encephalitis that tested positive for both anti-NMDAR and anti-MOG antibodies and that responded well to steroid therapy during the acute stage." (PMID 38895128, 2024). "In this study, we reviewed the efficacy of steroid therapy in 13 patients with encephalitis with coexisting anti-NMDAR and anti-MOG antibodies." (PMID 38895128, 2024). "In conclusion, when a patient with anti-NMDAR encephalitis or FLAMES is encountered in clinical practice, the possibility of coexistence of these diseases, with double-positive anti-NMDAR and MOG antibodies in the CSF and serum, should be considered." (PMID 37960781, 2023).
encephalitis (continued). "When a patient with anti-NMDAR encephalitis or FLAMES is encountered in clinical practice, the coexistence of these diseases with double-positive anti-NMDAR and MOG antibodies should be considered and adopt appropriate evaluation and treatment." (PMID 37960781, 2023). "This is the first report about subcutaneous ofatumumab treatment in MOG and NMDAR IgG double positive encephalitis with 12-month follow-up, depicting its potential as a therapeutic option." (PMID 37649484, 2023). "A systematic review showed that there have been more than 200 cases reported in the literature of either MOGAD co-existing with NMDAR encephalitis or dual positivity of MOG and NMDAR antibodies in encephalitis or MOGAD patients." (PMID 37789888, 2023). "Overlap syndromes of these two disease entities have been reported, i.e. either MOG immunoglobulin G (IgG) and demyelinating aspects have been found in patients with anti-NMDAR encephalitis, or vice versa NMDAR IgG in patients with demyelinating CNS disease." (PMID 36384491, 2022). "Therefore, for encephalitis without demyelination, the anti-MOG antibody itself may not be directly associated with the encephalitis and another unknown autoimmune disorder coexisting with anti-MOG antibody positivity may be responsible for the encephalitis." (PMID 36532000, 2022). "When MOG-IgG or NMDAR-IgG was present alone, the clinical characteristics were dominated by demyelination or encephalitis, respectively." (PMID 36009058, 2022). "In our study, 6 patients with concomitant anti-NMDAR antibodies and anti-MOG antibodies presented with clinical symptoms of both acute demyelinating diseases and anti-NMDAR encephalitis." (PMID 35874583, 2022). "However, the response to the treatment revealed that MOG antibody-associated cortical encephalitis was sensitive to glucocorticoids, which is consistent with the response to the treatment and clinical prognosis of MOGAD, but markedly different from anti NMDAR encephalitis." (PMID 36688157, 2022). "Other scholars also conducted that the presence of low positive MOG IgG was only meaningful in the correct clinical context such as in patients with ON, myelitis, ADEM, or encephalitis." (PMID 36352355, 2022). "Comparison of clinical characteristics between patients with concomitant positive MOG-Ab and patients with typical anti-NMDAR encephalitis." (PMID 34268281, 2021). "With positive MOG-IgG and NMDAR-IgG, we consider this case had MOGAD overlapping with anti-NMDAR encephalitis." (PMID 34691028, 2021). "This also applies to myelin-oligodendrocyte-glycoprotein (MOG) encephalomyelitis (MOG-EM), a novel entity associated with serum autoantibodies against MOG, which phenotypically overlaps with both NMOSD and MS or may present as acute demyelinating encephalomyelitis (ADEM) and encephalitis." (PMID 33324914, 2020). "In addition, anti-NMDAR encephalitis and anti-MOG IDDs could also occur simultaneously." (PMID 31866928, 2019). "The other eleven patients developed anti-NMDAR encephalitis and demyelinating features simultaneously (5 anti-AQP4 antibody positive, 2 anti-MOG antibody positive)." (PMID 28698711, 2017). "It highlights the importance of conducting MOG-IgG tests in children with encephalitis and bronchopneumonia despite negative infection screening." (PMID 42255904, 2026). "Myelin oligodendrocyte glycoprotein antibody disease (MOGAD) and anti-N-methyl-D- aspartate receptor (NMDAR) encephalitis pediatric cases are especially challenging due to phenotypic variability, limited literature, and the absence of standardized treatment protocols." (PMID 41884830, 2026). "Even though male patients with anti-NMDAR encephalitis have higher levels of CSF protein and are more frequently have overlapping anti-MOG antibodies, these factors do not appear to influence their condition or outcomes." (PMID 41584103, 2025).